NBR2 (neighbor of BRCA1 lncRNA 2)
Diseases named in the same sentence as NBR2 in open-access papers (continued):
Sharing a sentence is not in itself a finding about the gene and the disease.
cancer (16 papers, 2017 to 2026). A tumor composed of atypical neoplastic, often pleomorphic cells that invade other tissues. "In various human cancers, the expression of NBR2 is dysregulated and associated with clinical outcomes." (PMID 36233294, 2022). "NBR2 has emerged as a crucial regulator of cancer biology, and a promising diagnostic and therapeutic target." (PMID 34926299, 2021). "Further investigations underlying the NBR2 regulatory mechanisms in cancer are required for the materialization of its clinical application." (PMID 34926299, 2021). "Consistently, the NBR2 level was associated with the progression of these cancers." (PMID 34926299, 2021). "Here, we review the precise molecular mechanisms underlying NBR2-induced changes in cancer." (PMID 34926299, 2021). "The adverse effects of NBR2 may result from the type, stage, or genetic context of these cancers, underlining that antitumor therapeutic strategies targeting NBR2 should be applied modestly." (PMID 34926299, 2021). "Consequently, the loss of both BRCA1 and NBR2 genes could increase the risk of cancer development and impact the clinical follow‐up." (PMID 39783935, 2025). "NBR2 is also a promising therapeutic target, as NBR2 is involved in regulating the proliferation, migration, and survival of different cancer cells." (PMID 34926299, 2021). "Here, we review the role of lncRNA NBR2 in cancer biology, as well as emphasize its clinical application." (PMID 34926299, 2021). "Despite considerable progress in the understanding of NBR2 function, significant obstacles remain to be overcome for better realizing the role of NBR2 in cancer." (PMID 34926299, 2021). "Different regulatory elements drive the hypoxia-induced repression of BRCA1 and the activation of NBR2 in cancer cells." (PMID 34926299, 2021). "In HCC, NBR2 attenuates Beclin1-induced cytoprotective autophagy to inhibit cancer proliferation through the extracellular regulated protein kinase (ERK) and c-Jun N-terminal kinase (JNK) pathways, which provides novel insights on a treatment strategy for HCC." (PMID 34926299, 2021). "Nevertheless, it would be interesting to examine in more cases, if these mutation carriers show any multilocus phenotype, since recent findings argue that NBR2 is also involved in cancer pathways." (PMID 32629901, 2020). "Currently, a glucose starvation-induced lncRNA called NBR2 (the neighbor of BRCA1 gene 2) was found to be induced in cancer cells by the LKB1–AMPK pathway under energy stress conditions." (PMID 30134946, 2018). "lncRNA NBR2 is dysregulated in diversified cancers and modulates cancer evolvement." (PMID 35703318, 2022). "Moreover, NBR2 affects cancer cell sensitivity to antitumor drugs, as NBR2 expression is related to drug resistance." (PMID 34926299, 2021). "Moreover, NBR2 is crucial for glucose metabolism and affects the proliferation, survival, metastasis, and therapeutic resistance in different types of cancer." (PMID 34926299, 2021). "Finally, these studies will improve our understanding of the roles of lncRNA in cancer through the investigation of NBR2." (PMID 34926299, 2021). "In human cancers, NBR2 expression is dysregulated and correlates with clinical outcomes." (PMID 34926299, 2021). "NBR2 is involved in cancer progression based on its ectopic expression." (PMID 34926299, 2021). "In addition to affecting the activation of the AMPK pathway, lncRNA NBR2 can mediate the glucose metabolism of cancer cells by other mechanisms." (PMID 34926299, 2021). "The dual role of NBR2 in cancer biology is another challenge." (PMID 34926299, 2021). "In addition, glucose starvation in TME can also induce the expression of lncRNA NBR2 in cancer cells through the liver kinase B1 (LKB1)–AMPK pathway, and the precise mechanism will be discussed in the next section." (PMID 34926299, 2021). "Consistent with the BRCA1 gene, NBR2 expression is usually down-regulated in cancer." (PMID 34926299, 2021).
cancer (continued). "However, an opposite role of NBR2 in cancer progression has also been revealed." (PMID 34926299, 2021). "Thus, NBR2 may promote cancer cell glucose uptake by participating in alterable biological processes in response to different intracellular environments." (PMID 30134946, 2018). "In this study, although NBR2 was downregulated in HGSC tissues, which is consistent with its behavior in other cancer types, its overexpression promoted cell migration in vitro." (PMID 38571514, 2024). "NBR2, an lincRNA that was initially identified as a cancer suppressor, is involved in the regulation of EMT in different cancers." (PMID 34926299, 2021). "As such, NBR2 acts as a negative regulator of HCC, as it inhibits cancer proliferation, invasion, and migration." (PMID 34926299, 2021). "NBR2 in the cytoplasm can promote AMPK activity by interacting with AMPKα, thereby regulating the proliferation, apoptosis, and autophagy of cancer cells." (PMID 34926299, 2021). "Previous reports related with three lncRNAs (CBR3‐AS1, NBR2, and ADAMTS9‐AS2) in various cancers." (PMID 38571514, 2024). "Thus, the linc00473, NBR2, and LKB1/AMPK axis may play a pivotal role in cancer cells by regulating metabolic rearrangement." (PMID 30134946, 2018). "However, these deletions, which usually contain BRCA1, NBR2, BRCA1P1, and NBR1 genes, are not restricted to the NBR2 gene, and further studies are needed to confirm whether a specific deletion of the NBR2 gene determines cancer susceptibility." (PMID 34926299, 2021).
NBR2 also shares sentences with these, for which no sentence is quoted: acute liver failure (1 paper); atherosclerosis (1); colon cancer (1); gastric cancer (1); liver fibrosis (1); thyroid (1).